CCL2 (C-C motif chemokine ligand 2)
Diseases named in the same sentence as CCL2 in open-access papers (continued):
Sharing a sentence is not in itself a finding about the gene and the disease.
pulmonary fibrosis (continued). "Collectively, our data demonstrate, for the first time, that NFATc3 regulates pulmonary fibrosis by regulating CCL2 and CXCL2 gene expression in macrophages." (PMID 37523510, 2023). "Mechanistic studies revealed that NFATc3 is involved in the pathogenesis of pulmonary fibrosis by promoting CCL2 and CXCL2 production in response to damaged epithelial cells, IL-33 and Th2 cytokine stimulation." (PMID 37523510, 2023). "Neutralizing the CCR2 ligands in mice, Ccl2 and Ccl12, results in an attenuation of bleomycin-induced lung fibrosis." (PMID 35993367, 2022). "Increased expression of CCL2, at least in the context of pulmonary fibrosis, is induced by NFκB (and AP-1 subunit c-JUN)." (PMID 35806457, 2022). "Macrophages and fibroblasts express CCL2 / MCP-1, and its production is required for pulmonary fibrosis." (PMID 35168663, 2022). "Consistent with this, Ccl2 is considered one of the key factors involved in skin and lung fibrosis of BLM-treated mice." (PMID 33803282, 2021). "CCL2 is expressed in macrophages, alveolar epithelial cells and lung vascular endothelium in pulmonary fibrosis." (PMID 35011819, 2021). "Accordingly, in vivo models have subsequently demonstrated the importance of alveolar epithelial cells MCP-1/CCL2 secretion in lung fibrosis." (PMID 34093523, 2021). "Based on overwhelming evidence implicating CCL2/CCR2 in (experimental) pulmonary fibrosis, a trial with carlumab, an anti-CCL2 antibody was conducted in IPF." (PMID 34093523, 2021). "CCL2 is a chemokine for myeloid cells, and treatment with anti-CCL2 antiserum or gene transfer of a dominant negative Ccl2 attenuates lung fibrosis in mice." (PMID 34893592, 2021). "Combined with elevated SASP mRNA expression (including Ccl2, Cxcl10, Ccl17, Mmp2, Mmp9, and Mmp12) in sorted macrophages after irradiation, we confirmed that senescent macrophages were partly contributed to lung fibrosis." (PMID 34023858, 2021). "Together, these findings suggest Klf4 deletion in SMA+ cells worsens bleomycin-induced lung fibrosis at least partly by increasing secretion of CCL2." (PMID 34893592, 2021). "Among them, MPs from patients with a longer disease duration or pulmonary fibrosis presented a higher profibrotic profile and a lesser capacity to express CCL2, implied in the recruitment of immune cells." (PMID 33193304, 2020). "MCP-1/CCL-2 is a chemokine known to up-regulate collagen gene expression, being implicated in lung fibrosis." (PMID 32625168, 2020). "To determine this, we measured CCL2 production by ELISA in BLM-induced murine pulmonary fibrosis lungs that had received Treg adoptive transfer." (PMID 29690905, 2018). "CCL2-driven inflammation is known to promote fibrosis and collagen deposition in a number of disease states, including human pulmonary fibrosis, bleomycin-induced pulmonary fibrosis in rats and mice, and interstitial renal fibrosis in mice." (PMID 28077158, 2017). "CCR2-/- mice that have decreased amounts of CCL2 from anti-CCL2 gene therapy treatment are protected against bleomycin-induced pulmonary fibrosis." (PMID 24499286, 2014). "In a previous study, CCL2 was reported to contribute to the development of lung fibrosis by reducing IL6 levels." (PMID 23874655, 2013). "Taken together, this highlights the potential for an anti-CCR2/CCL2 approach at inhibiting human lung fibrosis through attenuating fibroblast activity directly as well as reducing downstream fibrocyte profibrotic activities." (PMID 22011363, 2011). "The importance of CCL2 as a key mediator for lung fibrosis also is supported by data from animal models showing a reduction and prevention of bleomycin-induced lung fibrosis by anti-CCL2 monoclonal antibodies or by pharmacologic blockade, respectively." (PMID 19615053, 2009). "Altered expression of CCL3 is implicated in disease states, including atherosclerosis, rheumatoid arthritis, adult T-cell leukemia, and, like CCL2, pulmonary fibrosis." (PMID 17888174, 2007).
pulmonary fibrosis (continued). "CCL2 and/or CCR2 are implicated in the genesis and progression of diseases such as coronary artery disease, autoimmune disease, and pulmonary fibrosis." (PMID 17888174, 2007). "CCL-2 attracts fibrocytes to distinct injuries, and interestingly, the interplay among TGF-β, CCL-2, and IL-13 has been observed in pulmonary fibrosis, suggesting that it may also play a role in tumor fibrosis." (PMID 40362499, 2025). "Previous studies have established a correlation between the elevated levels of CCL2 and the increased severity and progression of lung fibrosis in SSc patients, notably through its association with a high HRCT fibrosis score and poorer survival compared to healthy volunteers." (PMID 40621880, 2025). "Moreover, IL-10 induces fibrosis by fibrocyte recruitment and M2 macrophage activation dependent on the Ccl2/Ccr2 axis, with the abrogation of pulmonary fibrosis by treatment with anti-Ccl2 neutralizing antibodies in mice." (PMID 39768150, 2024). "CCL2 also contributes to receptor-mediated pulmonary fibrosis progression." (PMID 39850880, 2024). "CCL2 may not only exacerbate the early inflammation, but also directly mediate fibrocyte recruitment, thereby contributing to the development of pulmonary fibrosis." (PMID 37523510, 2023). "Fibrosis-related genes include Col1a1, Acta2, Fn1, and Tgfb1 gene, and senescence-related genes composed of Cdkn2a, Tnf, Serpine1, Ccl2, Mmp10, and Mmp12 gene, all of which reflected the intensity of lung fibrosis and senescence events in lung tissue and pulmonary fibroblasts." (PMID 35662697, 2022). "Animal studies have demonstrated that CCL2 deficient mice do not develop pulmonary fibrosis in response to bleomycin, a drug that induces fibrosis." (PMID 34771552, 2021). "CCL2 expression positively correlates with skin and lung fibrosis in SSc patients." (PMID 33803282, 2021). "CCL2 is highly expressed in the lungs of patients with lung fibrosis." (PMID 34771552, 2021). "IL-10 could induce lung fibrosis via promoting fibrocyte recruitment and M2 macrophage activation in a CCL2/CCR2 axis." (PMID 31105564, 2019). "Other regulators identified in this study may be shared by the various cell-types, including Ccl2 and Ccl12, which are known to influence lung fibrosis in rodents." (PMID 29347981, 2018). "During pulmonary fibrosis, CCL2 stimulates fibroblasts to deposit collagen through a TGF-β1-dependent mechanism while during inflammation acts as a chemoattractant for a variety of immune cells including macrophages, mast cells, eosinophils, and T helper 2 cells." (PMID 24499286, 2014). "Circulating fibrocytes could directly be attracted to the alveolar space because of the local expression of chemokines for fibrocytes (such as CCL2 or CXCL12) already demonstrated in lung fibrosis." (PMID 23341987, 2013). "Based upon clinical and experimental characterizations of cellular and molecular responses in human IPF, specifically exaggerated CCL2 expression, we have presented data, which indicate that AFSC attenuate increased CCL2 in BAL in an experimental model of lung fibrosis." (PMID 23967234, 2013). "Furthermore, in experimental models of lung fibrosis, increased expression of CCL2 attracts fibroblasts, and stimulates their collagen secretion and proliferation." (PMID 23967234, 2013). "Our findings demonstrate the efficacy of AFSC within the bleomycin injury model and provide data, which suggest a novel mechanistic role for AFSC regulation of CCL2 resulting in the inhibition of parenchymal remodeling and the development of pulmonary fibrosis." (PMID 23967234, 2013). "In a previous study, CCL2 was hypothesised to contribute to the development of lung fibrosis by reducing IL-6 level." (PMID 22754319, 2012).
pulmonary fibrosis (continued). "Transcriptomic data of people living with HTLV-1, HAM/TSP patients and idiopathic pulmonary fibrosis patients confirm in vivo expression of the in vitro gene signature, whereas single cell RNA-seq identified a unique myeloid subset in human lung, characterized by co-expression of CCL2/ISG15/CXCL10." (PMID 42026465, 2026). "CCL2 may serve as a potential therapeutic target for managing idiopathic pulmonary fibrosis." (PMID 39940903, 2025). "PAR1 activation on lung epithelial cells may enhance local CCL2 release in pulmonary fibrosis." (PMID 39768150, 2024). "In a mouse model of pulmonary fibrosis, Leucine-Rich Repeat Kinase 2 (LRRK2) expression is significantly reduced in alveolar type II epithelial (ATII) cells, and LRRK2-deficient ATII cells exhibit an enhanced ability to recruit profibrotic macrophages via the CCL2/CCR2 axis." (PMID 39850880, 2024). "In a recent in vivo study, bleomycin-induced AEC insult led to a significant increase in CCL2 and CCL12; in such cases, monocyte-oriented macrophages were recruited by these chemokines in the lung and ultimately promoted the exudate phenotype associated with lung fibrosis." (PMID 38461312, 2024). "Regarding CCL2 (which is also produced by MCs), it has been shown that it attracts fibrocytes to distinct injuries and, interestingly, the interplay among TGF-β, IL-13, and CCL2 has been observed in the context of pulmonary fibrosis, suggesting that may play a role also in tumor fibrosis." (PMID 35159157, 2022). "Notably, anti-CCL2 antibody treatment attenuated lung fibrosis in these mice, suggesting that targeting M2 macrophages may represent a promising therapeutic strategy for treating fibrosis." (PMID 32708044, 2020). "Thus emerges the importance of CCL2/CCR2 signaling in the pathogenesis of pulmonary fibrosis." (PMID 23967234, 2013). "In addition, a decrease of lung fibrosis was detected in CCL2 null mice when exposed to bleomycin." (PMID 19347046, 2009). "Metformin treatment also reduced BALF levels of CCL17 and CCL2, cytokines we previously reported as being upregulated in AT2I73T cells and increased in the SftpcI73T mouse model of lung fibrosis." (PMID 40591409, 2025). "Deficiency in NFATc3 significantly reduces the levels of fibrotic markers CCL2 and CXCL2 induced by BLM, attenuating BLM-induced pulmonary fibrosis and inflammatory response." (PMID 39301028, 2024). "Intriguingly, lung fibrosis was efficiently inhibited in ATII cell-specific Ccl12 knockout mice, and the expression levels of CCL2 and CCL7 were decreased in BAL fluid obtained from these mice." (PMID 37524875, 2023). "Taken together, these data support a critical role for NFATc3 in regulating the production of CCL2 and CXCL2 in macrophages during the BLM-induced pulmonary fibrosis progression in mouse models." (PMID 37523510, 2023). "CCR2 is the receptor of CCL2, CCL7, and CCL12, which plays an important role in the progression of pulmonary fibrosis." (PMID 36556326, 2022). "The elevated CCL2, CCL7, and CCR2 in the lung of the o-PF group suggest they are the important executors of pulmonary fibrosis in old rats, in addition to TGF-β." (PMID 36556326, 2022). "Recent studies showed that the CCL2/CCR2 axis has a vital role in the fibrotic formation in some diseases, including pulmonary fibrosis, renal fibrosis, and non-alcoholic liver fibrosis." (PMID 33614685, 2021). "However, it is still controversial whether CCL2−/− mice can be protected from pulmonary fibrosis." (PMID 33176882, 2020). "AT2 produced excessive monocyte chemotactic protein-1 (MCP-1, also known as C-C motif ligand 2 (CCL2)) that in turn promoted macrophage recruitments and TGFβ production leading to lung fibrosis." (PMID 32218238, 2020). "Previous studies showed elevated levels of CCL2, CCL3, and CCL4 in patients with mustard gas-induced pulmonary fibrosis." (PMID 30867053, 2019).
pulmonary fibrosis (continued). "In animal models of allergic asthma, idiopathic pulmonary fibrosis (IPF), and bronchiolitis obliterans syndrome (BOS), CCL2 expression and protein production are increased and the disease process is attenuated by CCL2 immuno-neutralization." (PMID 29456774, 2018). "CCL2 promotes the expression of COL1A1 protein and α-SMA proteins, suggesting that the mechanism of inflammation-induced pulmonary fibrosis may involve the regulation of COL1A1 and α-SMA by CCL2." (PMID 40606673, 2025). "Additionally, BAFF also promotes pulmonary interstitial fibrosis by acting as a potent inducer of TIMP-1, α-SMA, CCL2, and IL-6." (PMID 38637830, 2024). "IPF samples contain significantly more CCL2 and M-CSF than BALF from healthy volunteers, and Ccl2-/- mice are protected from bleomycin-induced pulmonary fibrosis, suggesting that M-CSF contributes to the pathogenesis of IPF through CCL2 production and activation of mononuclear phagocytes." (PMID 39768150, 2024). "Blocking IL-17A leads to reduced CCL2 expression in cpGVHD-related pulmonary fibrosis, though this effect is not observed in kidney diseases." (PMID 39850880, 2024). "Serum concentrations of pro-inflammatory factors [IFN-γ, IL-1β, IL-12, IL-6, IL-8, IL-18, IP-10, MCP-1, CC-chemokine ligand-2 (CCL-2), and CXCL-10] are positively connected with pulmonary fibrosis and significant lung tissue destruction in SARS-coronavirus patients, according to the latest research." (PMID 37124230, 2023). "Interestingly, NFATc3+/+ mice subjected to BLM-induced pulmonary fibrosis showed increased accumulation of fibrotic foci, extracellular matrix protein deposition, fibronectin, α-SMA, CCL2 and CXCL2 production." (PMID 37523510, 2023). "Then, we assessed whether NFATc3 regulates the production of CCL2 and CXCL2 in mouse in vivo pulmonary fibrosis models." (PMID 37523510, 2023). "We previously reported that in lung pathology of ILD in patients with microscopic polyangiitis, chemokine C-C motif ligand 2 (CCL2)-producing CD68+/CD163+ macrophages infiltrate the alveoli, and serum CCL2 levels significantly correlate with the progression of lung fibrosis." (PMID 36077067, 2022). "However, UPR can also participate in pulmonary fibrosis by increasing the expression of profibrotic mediators, such as TGF-β1, platelet-derived growth factor (PDGF), CXCL12, and CCL2." (PMID 35935869, 2022). "Following bleomycin-induced lung injury, Il11−/− mice are protected from pulmonary fibrosis and exhibit lesser ERK, STAT3 and NF-kB activation, reduced Il1b, Timp1, Ccl2 and diminished IL6 expression, both at baseline and after injury: placing Il11 activity upstream of IL6 in this model." (PMID 34239012, 2021). "For instance, the cytokines TNF-α, IL-1α, IL-1β, and IL-6, and the chemokines CCL2 (MCP-1), CCL5 (RANTES), and CXCL2, have been shown to play pro-fibrotic roles in bleomycin-induced lung fibrosis in mice and in certain human fibrotic lung diseases, such as IPF and asbestosis." (PMID 32185174, 2020). "Similarly, Murine CCL12 (also known as MCP-5) is an analog of human CCL2, and CCL2 and its receptor CCR2 are one of the most widely studied chemokines and receptors in pulmonary fibrosis." (PMID 33176882, 2020). "Notably, CCL2 and CCL5 upregulation was found to precede skin and lung fibrosis in a mouse model that recapitulates the pathology of SSc53." (PMID 29619245, 2018). "Thus, various studies have shown that the expression of CCL-2 is markedly increased in IPF and in various models of pulmonary fibrosis and that the neutralization of this chemokine or its receptor significantly attenuated fibrotic response." (PMID 26934369, 2016). "CCL-2 was upregulated in BLM-treated n/i/eNOS−/− mice compared to BLM-treated WT mice, and therefore, the CCL-2/NO pathway was considered as an alternative pathway leading to BLM-induced pulmonary fibrosis in this study." (PMID 25092105, 2014).
pulmonary fibrosis (continued). "Moreover, IL-33 treatment increases CCL2 and CXCL2 production in NFATc3+/+ macrophages, but not in NFATc3+/- mice, suggesting that NFATc3 regulates pulmonary fibrosis by regulating CCL2 and CXCL2 expression in macrophages." (PMID 39850880, 2024). "Finally, group IV comprised several mediators of pulmonary fibrosis as IL-8/CXCL8, monocyte chemoattractant protein-1 (MCP-1)/CCL-2, monokine induced by IFN-γ (MIG)/CXCL9 and fibroblast growth factor-(FGF)-9, highly expressed in IPF patients but not in the other two groups." (PMID 38111019, 2023). "Furthermore, consistently unique cytokine expression patterns of regenerative and growth factors (CCL2, CCL11, IL6, IL12B, and CXCL8) may indicate activation of pulmonary fibrosis signaling pathways after aberrant inflammatory response." (PMID 35145507, 2021). "Indeed, CCL-2 is a chemoattractant for fibrocytes, and CCL-3 has been involved in bleomycin-induced recruitment of bone marrow-derived macrophages and fibrocytes, and the subsequent development of pulmonary fibrosis." (PMID 24885771, 2014). "Moreover, pulmonary fibrosis was suppressed by neutralizing CCL12 but not CCL2." (PMID 36012611, 2022). "Similarly, MPs isolated from SSc patients with lung fibrosis showed a greater profibrotic profile, with an upward trend for Col1a1/MMP1 (median of 1.59 vs. 0.65, p=0.1) and Col1a2/MMP1 ratio (median of 2.42 vs. 0.91, p=0.07), but reduced ability to induce CCL2 (median of 0.89 vs. 1.51, p<0.05)." (PMID 33193304, 2020). "In controls with ILD due to other diseases, fewer abnormalities were observed; however; some cytokines/chemokines, such as CCL2 and CCL3, were increased in idiopathic ILD as well as in SSc-associated ILD, indicating an important, but nonspecific contribution of these chemokines in lung fibrosis." (PMID 19615053, 2009). "Despite Carlumab’s lack of efficacy in treating progressive idiopathic pulmonary fibrosis (IPF), these findings suggest that newer agents are needed to suppress CCL2-mediated signaling more effectively." (PMID 39076996, 2024). "Mice lacking CCL2 are protected from bleomycin-induced dermal fibrosis, while mice lacking the CCL2 receptor CCR2 are protected from bleomycin-induced lung fibrosis." (PMID 23845159, 2013). "In addition, CCL12 knockout mice were found to have a compensatory increase in the expression of CCL2 and CCL7 in lung tissue and bronchoalveolar lavage fluid, and CCL12 knockout did not protect mice from the formation of pulmonary fibrosis." (PMID 33176882, 2020).